PRMT5 (protein arginine methyltransferase 5)
Diseases named in the same sentence as PRMT5 in open-access papers (continued):
Sharing a sentence is not in itself a finding about the gene and the disease.
cancer (continued). "PRMT5 catalyzes the vast majority of SDMA posttranslational modifications on histones, splicing factors, transcription factors and enhancer-binding proteins, metabolic enzymes, and cell signaling proteins implicating its role in cancer progression and survival." (PMID 38000655, 2024). "Since first generation PRMT5i do not target the PRMT5-MTA complex, it is not clear yet whether they will be clinically active in patients with MTAP-deficient cancers." (PMID 37502925, 2023). "Additionally, PRMT5 helps maintain the TME, which supports cancer cell survival and immune evasion." (PMID 36980950, 2023). "Furthermore, the PRMT5 inhibitor GSK3230591 is more sensitive in some cancer cells that do not express MTAP." (PMID 36980950, 2023). "Although not included in this article, PRMT5 also regulates cancer cell proliferation." (PMID 36980950, 2023). "Therefore, PP2A-activating compounds may be effective in cancers with functional NDRG2 and may synergize with PRMT5 inhibiting compounds, while NDRG2 deletions may render this strategy ineffective." (PMID 35118387, 2022). "It is worth mentioning, however, that lack of PRMT1 and PRMT5 elevation in tumors might not necessarily mean that enzyme expression is not affected by cancer." (PMID 34439753, 2021). "Finally, the mechanism of action of MTDIA was investigated by assessing PRMT5 activity in treated mice and by generation of an MTAP inhibitor-resistant cell line of FaDu cancer cells, revealing amplification of MAT2A, a known target in MTAP−/− cancers." (PMID 33893330, 2021). "Additionally, PRMT5 inhibitors JNJ-64619178 and GSK3326595 are currently in phase I clinical trials (ClinicalTrials.gov identifier numbers NCT03573310 and NCT03614728, respectively) for patients with advanced cancers." (PMID 33691794, 2021). "One possible explanation is that the methylation target of PRMT5 in different cancers may not be the same." (PMID 34522232, 2021). "However, in some kinds of cancer cells, such as B16 cells, PRMT5 expression is not correlated with cell proliferation." (PMID 34522232, 2021). "Moreover, PRMT5 repressed the tumor suppressor F-box and WD repeat domain containing 7 (FBW7), which led to elevating c-Myc expression levels and promoting aerobic glycolysis and cancer cell proliferation." (PMID 33495409, 2021). "Indeed, Arg110 methylation of PDCD4 by PRMT5 modulates PDCD4 subcellular translocalization from the nucleus to the cytoplasm and facilitates its interaction with eIF4A in the cytoplasm, leading to enhanced cancer cell viability." (PMID 34006904, 2021). "Finally, we identified a subset of EMT markers regulated by PRMT5 in MM, including E‐cadherin, N‐cadherin, α‐smooth muscle actin and MMP9, indicating that targeting PRMT5 could hamper this crucial process for cancer progression." (PMID 32301278, 2020). "In-depth mechanistic explorations indicated that PRMT5 could regulate aerobic glycolysis via the regulation of cMyc stability by epigenetically silencing the expression of FBW7, a ubiquitin ligase and tumor suppressor with decreased expression in cancer cells." (PMID 30922330, 2019). "The authors show also a positive correlation between the expression of MEP50/PRMT5 and that of GLI1 target genes in several HH-dependent cancers, and demonstrate that targeting of MEP50/PRMT5 complex may synergize with SMO inhibitors in suppressing cancer cell proliferation and invasion." (PMID 31244888, 2019). "Furthermore, ectopic expression of PRMT5 or KLF4 in MCF-7 cells leads to cellular accumulation of methylated KLF4 protein, which reduces transcription of the pro-apoptotic gene BAX, thereby promoting cancer cell growth and survival." (PMID 30613353, 2018).
cancer (continued). "Therefore, in cancer cells with ΔNp63, the insufficient expression of LCE1C may be defective in inhibiting the oncogenic activity of PRMT5." (PMID 29559659, 2018). "Hence, it appears that PRMT5 activity specifically affects self-renewal of cancer rather than normal mammary stem cells." (PMID 29262329, 2017). "Thus, it is possible that Omomyc may affect the PRMT1/PRMT5/MEP50/CHTOP complex, impairing cancer-related gene expression." (PMID 26563484, 2015). "To explore this hypothesis, we assessed the effect of the a potent and selective, clinical PRMT5 inhibitor, GSK3326595, on DNA damage response pathways and evaluated efficacy in combination with the PARP inhibitor, niraparib, in HR-proficient human cancer models." (PMID 37596538, 2023). "However, we demonstrated that targeting PRMT5 induced PD-L1 expression in cancer cells, and it compromised CD8 T cell antitumor immune responses in immunocompetent mice, suggesting that PRMT5 inhibition may have different effects on the immune cell functions in different tumor types." (PMID 35111150, 2021). "Since SREBP1c has been shown to interact with PRMT5 in both HEK293 and HepG2, it is tempting to speculate that SREBP1c might also undergo the same type of symmetric methylation, which might enhance its stability and contribute to elevated lipid metabolism and cancer cell growth." (PMID 30613353, 2018). "PRMT5 inhibitors, namely SAM competitive inhibitors, SAM non-competitive inhibitors, and substrate-competitive inhibitors, have been utilized for cancer treatment." (PMID 40869229, 2025). "Cancer cells with a homozygous deletion of the MTAP gene do not degrade MTA, which is accumulated in cells and inhibits the activity of the PRMT5 enzyme." (PMID 41465382, 2025). "Despitethe genetic evidence for a synthetic lethal relationshipbetween PRMT5 and MTAP deletion, the first generationof PRMT5 inhibitors that were developed do not demonstrate selectivityfor MTAP-null cancer cell lines." (PMID 38595098, 2024). "Among the enzymes identified to catalyse the methylation of p65 arginine residues, protein arginine methyltransferase 5 (PRMT5) holds prominence, PRMT5 plays a crucial role in normal physiology and cancer development, particularly in haematologic malignancies." (PMID 39050887, 2024). "In summary, PRMT5 is a key regulator of RNA splicing, and as an effector molecule for SDMA marks deposited by PRMT5, it is not surprising that SND1 is also integral to the maintenance of normal splicing programs that can go awry in a cancer setting." (PMID 33768972, 2021). "This interplay between type I and type II PRMTs has recently been shown to have therapeutic value for cancer treatment and thus, it is not surprising that PRMT1 is synthetic lethal to PRMT5 deletion." (PMID 33691794, 2021). "Although pharmacological treatments directly targeting PRMT5 are not yet available, some Epizyme inhibitors such as EPZ015666 carry promise for utilization in cancer." (PMID 30922330, 2019). "However, PRMT5 knockdown did not affect the transcriptional activity of transcription factors NF-κB and HIF156, which are known to be activated in other cancer types." (PMID 38760429, 2024). "The silencing of PRMT5 or MEP50 expression with each specific shRNA impaired cell proliferation and the stabilization of the HSP90 client proteins AKT and NEMO in NDRG2low ATL and cancer cell lines, but not in NDRG2-expressing cell lines." (PMID 38474089, 2024). "Protein arginine methyltransferase 5 (PRMT5), an enzyme that catalyzes symmetric and asymmetric methylation on arginine residues of histone and non-histone proteins, is overexpressed in many cancers." (PMID 34124017, 2021).
cancer (continued). "Therefore, the identification of nuclear TLR3 provides new insight into non-classical functions of innate immune sensors in cancer, and JAK1/TLR3/PRMT5/c-Myc axis may sever as a potential prognostic indicator and therapeutic target to overcome chemoresistance." (PMID 40675966, 2025). "Furthermore, although MTA levels are elevated in MTAP-deleted cancers, the different levels of SAM, MTA, and other metabolic intermediates may vary across cells and tissues so that PRMT5 vulnerability may be impacted non-uniformly even in genetically defined backgrounds." (PMID 41339334, 2025). "In the case of cancer cells with truncated mutant p63 proteins such as ΔNp63, the insufficient expression of LCE1C may be defective in inhibiting the oncogenic activity of PRMT5 because ΔNp63 harbors T281 in the DNA-binding domain but not T46 in the transactivation domain." (PMID 29559659, 2018).
tumor (321 papers, 2009 to 2026). "It makes tumor cells more susceptible to PRMT5- and MAT2A-inhibiting drugs as well as to pemetrexed (antifolate therapy)." (PMID 40227771, 2025). "H&E staining of the liver tissues revealed that deletion of even one Prmt5 allele led to massive necrosis in some tumor regions with inflammatory cell infiltration (as evidenced by macrophage surrounding of the necrotic areas)." (PMID 38853928, 2025). "PRMT5 is an oncogene involved in protein arginine methylation that is associated with tumor cell proliferation, differentiation, invasion, and migration." (PMID 40723820, 2025). "Inhibition of ULK1 blocks autophagy induced by PRMT5 deficiency and enhances sensitivity to PRMT5 inhibitors, thereby reducing tumor drug resistance." (PMID 39247603, 2024). "Multiple studies have shown that PRMT5 expression is correlated with overall survival and is associated with tumor metastasis." (PMID 39614393, 2024). "On the other hand, some studies have also found that the expression levels of PRMT2 and PRMT5 are down-regulated in tumors, and their functions are associated with inhibition of tumor cell proliferation and invasion." (PMID 38663941, 2024). "PRMT5 plays a complex role in oncogenesis, as its methylation of proteins is implicated in both tumor promotion and suppression across various tumor types." (PMID 39337530, 2024). "This approach differs from the tumor genetic deficiency of synthetic lethality that converges on PRMT5 inhibition." (PMID 38000655, 2024). "The data shown here indicate that loss of PRMT5 activity selectively enhances tumor cell radiosensitivity through an inhibition of DNA double strand break (DSB) repair." (PMID 39068290, 2024). "Previous research findings have indicated that protein arginine methyltransferase 5 (PRMT5) is closely linked to tumor occurrence and belongs to the type II protein arginine methyltransferase family." (PMID 39366935, 2024). "In the present study, we showed in two independent cohorts of BC specimen that a high expression of PRMT5 in the nucleus of tumor cells was associated with a prolonged survival for patients treated with Tam but not with AI." (PMID 37458145, 2023). "Our analysis of PRMT5 expression in two cohorts of BC patients clearly showed that its presence in abundance in the nucleus of tumor cells is associated with an increase in survival in patients treated with Tam." (PMID 37458145, 2023). "QTR4 patients (red line), i.e., those with tumor tissues expressing either PRMT5 or APE1 at higher levels, were associated with poorer outcomes compared to QTR1 patients (blue line)." (PMID 37887269, 2023). "We found that PRMT5 was significantly upregulated in tumor tissues and that high PRMT5 gene expression was significantly associated with worsened overall survival (log-rank test, P = 0.019)." (PMID 37861293, 2023). "BRG1 association with PRMT5 has been demonstrated to function as a tumor suppressor in correspondence with certain target genes." (PMID 36769189, 2023). "PRMT5 is also important in MBD2–NuRD-associated gene silencing in tumor cells through PRMT5-mediated symmetric methylation of histone arginine residues and is associated with MBD2a but not MBD2b in HeLa cell extracts." (PMID 37307480, 2023). "Increased PRMT5 protein expression is associated with tumor growth in numerous malignancies by reducing the activity of tumor suppressing miRNAs via histone tail modifications." (PMID 36003783, 2022). "Multiple clinical trials are currently being conducted which are focused on PRMT5 or MTA2 inhibition designed to take advantage of the high intracellular arginine levels in the MTAP deficient tumor cells." (PMID 35881043, 2022). "Taken together, these results revealed a causal relationship between the loss of PRMT5 and antral tumorigenesis, supporting a tumor-suppressor role of PRMT5 in vivo, at least in antrum." (PMID 35864961, 2022).
tumor (continued). "There were significant associations between PRMT5 levels with tumor size, pathological staging, and metastasis." (PMID 34124017, 2021). "We also found that PRMT5 deficiency in tumor cells enhanced the secretion of the cytokines IFN-γ and TNF-α by CD4+ T cells, and the expression pattern of above checkpoints on CD4+ T cells was similar to that on CD8+ T cells." (PMID 34522232, 2021). "As highlighted above, PRMT5 is overexpressed in a large number of different tumor types, and the inhibition of PRMT5 has been linked to tumor regression in mouse models." (PMID 33768972, 2021). "The interest in developing PRMT5 inhibitors stems from the observation across multiple tumour types that high expression of PRMT5 is associated with worse prognosis and its inhibition in various preclinical models has led to PDAC regression." (PMID 34680285, 2021). "Protein arginine transferase 5 (PRMT5) has been implicated as an important modulator of tumorigenesis as it promotes tumor cell proliferation, invasion, and metastasis." (PMID 35111150, 2021). "PRMT5 plays a complex role in oncogenesis, as it is known to control expression of genes implicated in both tumor promotion and suppression." (PMID 32743345, 2020). "MTAP-deficient tumor cells are more susceptible toward PRMT5 inhibition than MTAP-competent ones, so using PRMT5 inhibitors is an opportunity to specifically target this tumor cell group." (PMID 33123121, 2020). "In contrast, in vivo depletion of PRMT5 substantially slowed tumor growth and in some cases caused regression." (PMID 29262329, 2017). "We showed that PRMT5 protein is overexpressed in HCC tumor tissues, and its elevated level is associated with worse prognosis in patients with HCC." (PMID 26541651, 2015). "Interestingly, we discovered that PRMT5 deficiency led to a decrease in CXCL10 expression in tumor cells." (PMID 41463372, 2025). "Notably, compared to the C57BL/6 mice group, there was a significant increase in tumor volumes and weights in the PRMT5 knockdown groups with CD8 deficiency, which corresponded to lower survival rates than those observed in the control group." (PMID 41463372, 2025). "Therefore, while GSK3326595 induced significant apoptosis in normal intestinal and colonic tissue, the combination of MTDIA and AG-270 did not, although both regimens were equally effective in reducing tumor growth through comparable loss of PRMT5 activity." (PMID 38000655, 2024). "Moreover, the mouse xenograft assay showed that compared to PRMT5-WT, PRMT5-3A mutation significantly suppressed tumor growth." (PMID 37173967, 2023). "Besides, another study focusing on the genomic profiling and functional characterization of tumor cell lines revealed that MTAP loss relied on PRMT5." (PMID 37091983, 2023). "This metabolite accumulation in MTAP-deficient tumor cells led to sensitivity to PRMT5 targeting." (PMID 37091983, 2023). "Furthermore, the function of T cells was tested through flow cytometry, and we found that PRMT5 deficiency in tumor cells enhanced IFN-γ, TNF-α and granzyme B secretion by CD8+ T cells." (PMID 34522232, 2021). "PRMT5, which is the predominant type II methyltransferase-targeting arginine methylation, is upregulated in a variety of hematological malignancies and its overexpression is associated with tumor aggressiveness and poor overall survival." (PMID 34531375, 2021). "Notably, along with PRMT5 deficiency in tumor cells, the expression of PD-1 and TIM-3 on CD8+ T cells was decreased and LAG-3 expression had a declined trend." (PMID 34522232, 2021). "Importantly, through these interactions and its frequent overexpression in several tumor types including CRC, PRMT5 dysregulation has been linked to tumor cell proliferation, migration, epithelial-to-mesenchymal transition (EMT), invasion and metastasis." (PMID 32985589, 2020). "PRMT5 overexpression was associated with tumor size (P = 0.003)." (PMID 29441724, 2018).